YTHDF2 (YTH N6-methyladenosine RNA binding protein F2)
Diseases named in the same sentence as YTHDF2 in open-access papers (continued):
Sharing a sentence is not in itself a finding about the gene and the disease.
tumor (continued). "Conditional deletion of Ythdf2 in Foxp3+ Tregs curtailed tumor growth without systemic autoimmunity by reducing intratumoral Treg suppressive function via an m6A–NF-κB axis that reduces." (PMID 41280938, 2025). "Additionally, the correlation between YTHDF2 and KI67 reinforced its potential involvement in tumor proliferation." (PMID 41323282, 2025). "Conversely, YTHDF2 overexpression inhibits HCC cell growth and proliferation by binding directly to the m6A modification site on the 3′-UTR of EGFR mRNA, promoting its degradation and halting tumor progression." (PMID 40271153, 2025). "The mRNA stability of MCM2 and MCM5, which is reliant on m6A and may considerably suppress tumor growth and progression, is promoted by OGT‐mediated O‐GlcNAc of YTHDF2 at Ser263." (PMID 40919129, 2025). "YTHDF2 and ALKBH5 promote tumor progression through metabolic disorders and oncogene activation." (PMID 41446042, 2025). "Sh‐YTHDF2 and DNase I promoted SLC2A3 expression in tumours and had a superimposed effect." (PMID 39865544, 2025). "In addition to the oncogenic roles of YTHDF1 and YTHDF2, knocking down HnRNPL can reduce the stability of YY1 mRNA in CRPC and inhibit the migration of tumor cells." (PMID 40830264, 2025). "Furthermore, single cell sequencing data from GC patients revealed an inverse correlation between the expression of YTHDF1 and YTHDF2 and that of IRF1, particularly within tumor cells, T cells, and macrophages." (PMID 39587835, 2025). "Moreover, due to hypermethylation of specific sites in CRC, YTHDF2/3 degrades the lncRNA CARMN, thereby relieving inhibition of the downstream oncogenic axis and accelerating tumor progression." (PMID 41446042, 2025). "In regulatory T cells (Tregs), the m6A reader YTHDF2 maintains fitness under inflammatory stress; its deletion reduces intratumoral Treg survival and diminishes PD-1-high expressing Treg populations, unleashing CD8+ responses and slowing tumor growth." (PMID 41280938, 2025). "This discovery not only provides new insights into the molecular mechanisms of CCA but also suggests potential targets for the development of innovative treatment strategies, such as drugs targeting LINC00511, YTHDF2, or SOX2 to disrupt this loop and curb tumor progression." (PMID 39445001, 2024). "The absence of YTHDF2 in tumors impairs tumor glycolytic metabolism, therefore enhancing the mitochondrial respiration of CD8+ T cells to strengthen antitumor capabilities." (PMID 39372415, 2024). "The absence of YTHDF2 in Treg cells of the tumor microenvironment leads to an increase in CD8+ T cell infiltration and the expansion of the antitumor CD4+ TH1 subset." (PMID 39372415, 2024). "Knockdown of ALKBH5 increased the enrichment of m6A nearby the stop codon and 3’UTR region of CD274 mRNA, thereby promoting the decay of CD274 mRNA in a YTHDF2-dependent manner, but ALKBH5 has minimal inhibitory effects on tumor cell PD-L1 expression at the translational level." (PMID 38365891, 2024). "YTHDF2 stabilizes the CX3CL1 transcript in an manner dependent on m6A, modulating the interaction between CD8 T cells and thereby promoting treatment-induced anti-tumor immune responses in the liver." (PMID 39593172, 2024). "The analysis further indicated that three m6A readers are differentially expressed in the mCRPC tissues, where the YTHDF2 gene showed significant upregulation, while the NUDT21 and SRSF10 genes showed significant downregulation in mCRPC compared to both the localized tumor and normal tissues." (PMID 38610981, 2024). "In summary, METTL3 and YTHDF2 may act as “oncogenes” in HCC, facilitating tumor angiogenesis and malignant progression." (PMID 39295872, 2024). "We found that depletion of YTHDF2 greatly inhibited HCC growth, as reflected by the decrease in tumor volume, tumor weight, and immunohistochemical (IHC) staining of Ki67, which was recovered by re-expressing YTHDF2-WT but not YTHDF2-S263A." (PMID 36765030, 2023).
tumor (continued). "When silencing YTHDF2 and overexpressing NEDD4, the growth rate of the tumor was restored." (PMID 37605223, 2023). "These outcomes suggest that the tumor suppressor effect of ANXA10 is related to m6A; ANXA10 may regulate HNRNPA2B1, IGF2BP3, METTL3, RBM15, YTHDF1 and YTHDF2 to affect the methylation level of LIHC." (PMID 36709331, 2023). "Ablation of YTHDF2 in TAMs suppressed tumor growth by reprogramming TAMs toward an antitumoral phenotype and increasing their antigen cross-presentation abilities, which in turn enhanced CD8+ T cell-mediated anti-tumor immune responses." (PMID 37359522, 2023). "Unlike YTHDF2, IGF2BPs identify m6A alteration under normal and stress conditions to alter gene regulation and tumor biology via their K homologous domains." (PMID 36831377, 2023). "In this study, we screened the MeRIP‐seq, YTHDF2‐RIP‐seq, and identified that the upregulated circFUT8 in LUAD tumor samples, derived from the exon 3 of FUT8, could be recognized by m6A reader protein YTHDF2." (PMID 37669906, 2023). "It has been shown that YTHDF2 is upregulated in GSCs and GBM tumours." (PMID 37444417, 2023). "Further investigation verified that YTHDF2 could recognize the abundance of m6A-modified mRNA of LHPP and NKX3-1 induced by METTL3 and degrade them, thereby promoting AKT phosphorylation and tumour progression." (PMID 37284313, 2023). "Overexpression of YTHDF2 positively activates the mTOR/AKT pathway and regulates the progression of EMT which may act as a tumor promoter to induce LUSC cell proliferation and invasion." (PMID 34996459, 2022). "In addition, the knockdown of YTHDF2 and EPHB3 or the knockdown of YTHDF2 and TNFAIP3 promoted the tumor growth in xenograft model under TMZ treatment compared with YTHDF2 silence alone." (PMID 35582627, 2022). "Interestingly, the role of YTHDF2 was also found to be related to inhibition of tumor necrosis factor (TNF), which subsequently suppressed apoptosis of tumor cells." (PMID 35382893, 2022). "As a result, there was a negative correlation between YTHDF2 expression and immune scores, stromal scores and estimated scores, and a positive correlation with tumor purity in most cancers except LGG and PPAD." (PMID 36120577, 2022). "We investigated whether YTHDF2 overexpression activates key signaling pathways in LUSC cells, such as the ERK/MAPK and mTOR/AKT signaling pathways known to play a role in tumor proliferation and survival." (PMID 34996459, 2022). "Moreover, overexpression of YTHDF2 results in activation of the YTHDF2-MYC-IGFBP3 axis in in vitro and in vivo tumor growth." (PMID 36012529, 2022). "To further validate the results, we obtained 60 paired tumor tissues and adjacent normal tissues of ESCC, and qRT-PCR was used to determine the expression pattern of METTL3, METTL14, WTAP, FTO, ALKBH5, YTHDF1 and YTHDF2." (PMID 35399719, 2022). "Taken together, YTHDF2 could modulate the Hippo/YAP signaling pathway to inhibit EMT, thereby suppressing tumor migration and invasion in some cancers." (PMID 35382893, 2022). "In addition, YTHDC1, YTHDF1, YTHDF2, IGF2BP3, HNRNPA2B1 and NKAP were confirmed by two databases to be positively correlated with tumor stage, which deserved more attention in the treatment of HCC." (PMID 35963644, 2022). "The results indicated that compared with ANT, the level of YTHDF2 mRNA in tumour tissues was not significantly increased; however, IHC staining showed that YTHDF2 protein levels were notable upregulated in CRC tissues compared with ANT." (PMID 34709763, 2021). "Notably, the expression of YTHDF2 protein is significantly increased in GBM and correlates with tumor grade." (PMID 33420027, 2021).
tumor (continued). "YTHDF2, downregulated by hypoxia, can suppress HCC progression through binding m6A sites of EGFR 3'UTR and inducing its degradation, and consequently suppresses cell proliferation, tumor growth, and activation of MEK and ERK in HCC cells." (PMID 33390849, 2021). "Moreover, the ablation of YTHDF2 in the cells reduced tumor growth of GSC11 and GSC7-2 cells as determined by in vivo intracranial tumor assay." (PMID 33420027, 2021). "Another study identified that the downregulation of YTHDF2 was specifically induced by hypoxia in HCC cells, and overexpression of YTHDF2 could inhibit cell proliferation and tumor growth in HCC cells." (PMID 34421350, 2021). "Furthermore, we confirmed that the control tumor xenografts have very low expression of LXRα and HIVEP2 proteins but depletion of YTHDF2 increased the expression of LXRα and HIVEP2." (PMID 33420027, 2021). "Unlike enhancing downstream target mRNA stability, METTL3 has been reported to combine with the m6A “reader” YTHDF2 to promote the degradation of PTEN mRNA and increase tumour malignancy, and subtly, the oncogenic lncRNA LINC00470 serves as an accelerator in this process." (PMID 35004679, 2021). "Tumor suppressors NKX3.1 and LHPP were the precise targets of METTL3 and YTHDF2." (PMID 34899855, 2021). "YTHDF2, another member of the YTH family, acts as a tumour suppressor gene." (PMID 34246319, 2021). "YTHDF2 directly binds to the m6A modification site of EGFR 3′-UTR, promotes the degradation of EGFR mRNA, and inhibits the proliferation of cancer cells and tumor growth." (PMID 33552994, 2020). "Moreover, the tumour metastasis related genes whose levels were substantially affected by SETD7 were consistent with the roles of METTL3 and YTHDF2 in EMT progression." (PMID 32126149, 2020). "A comparison of all results showed that the HNRNPC, WTAP, YTHDF2, and YTHDF1 were up-regulated in tumor samples and might influence the tumorigenesis of GBM." (PMID 33134160, 2020). "YTHDF2 silencing robustly facilitated tumor growth and metastasis in NPG (NOD-PrkdcscidIl2rgnull) mice, and this was partially due to the effects on cell proliferation and tumor angiogenesis." (PMID 31735169, 2019). "In concert with this, redundant expression of catalytically dead YTHDF2 failed to inhibit in vivo tumor development." (PMID 31735169, 2019). "Furthermore, skin-specific Ythdf2 deletion accelerated skin tumorigenesis induced by chronic UVB irradiation in both male and female mice, demonstrating an inhibitory role of YTHDF2 in tumor initiation." (PMID 41224760, 2025). "Similarly, when YTHDF2 forms a complex with CBSLR/YTHDF2/CBS, it destabilizes CBS mRNA in an m6A-dependent manner, leading to ACSL4 degradation via the ubiquitin-proteasome pathway and inhibiting ferroptosis in the hypoxic tumor microenvironment." (PMID 40001550, 2025). "Specifically, YTHDF2, by interacting with RBM4, facilitates the degradation of m6A-modified mRNAs of Signal Transducer and Activator of Transcription 1 (STAT1), thereby inhibiting the polarization of M1 TAMs, consequently diminishing both the innate and adaptive anti-tumor immunity of TAMs." (PMID 39342406, 2024). "Protein levels were verified by extracting subcutaneous tumor proteins, where the expression levels of the EMT-related proteins N-cadherin, TWIST1 were decreased and E-cadherin was increased in the shYTHDF2 group, while the opposite trend was shown in the YTHDF2 overexpression group." (PMID 39593172, 2024). "Besides, A/Lipo/si‐YTHDF2 specifically inhibits the expression of YTHDF2 in tumor tissues, without affecting normal liver tissues and other organs." (PMID 38247171, 2024). "The small molecule inhibitor DC‐Y13‐27, identified through screening and targeting YTHDF2, can overcome MDSC‐induced immunosuppression and improve the efficacy of IR and/or anti‐PD‐L1 combination therapy, offering a new combined treatment strategy for tumour immunotherapy." (PMID 39135292, 2024).
tumor (continued). "YTHDF2 is detected to be downregulated in colorectal cancer (CRC), and it has been found to mediate the degradation of X inactivate-specific transcript (XIST), a long non-coding RNA, which may contribute to accelerated tumor growth and metastasis in CRC." (PMID 39342406, 2024). "We showed that tumor tissues had higher expression of YTHDF2 versus adjacent normal tissues." (PMID 37515378, 2023). "In addition, YTHDF2 could also speed up YAP mRNA degradation through the Argonaute 2 (AGO2) system, inhibiting tumor cell proliferation and metastasis to mitigate disease progression." (PMID 36870954, 2023). "In addition, YTHDF2 could inhibit the phosphorylation of STAT3 and the expression of Serpin E2, thereby reducing tumor growth and angiogenesis and resisting the occurrence of inflammatory cancer progression." (PMID 35382893, 2022). "In cervical cancer (CC), knockdown of YTHDF2 significantly increased the expression and stability of GAS5, a tumor suppressor gene, thereby inhibiting the proliferation, migration and invasion of CC cells in vitro and suppressing the tumor growth and metastasis of CC in vivo." (PMID 35382893, 2022). "We explored the relationship between YTHDF2 expression and various immune cells as well as immune markers in LGG by employing the TISIDB and TIMER database, the TISIDB analysis result indicated that YTHDF2 expression was significantly correlated with 28 tumor-infiltrating lymphocytes." (PMID 35661004, 2022). "Moreover, YTHDF2 could also accelerate the degradation of YAP mRNA through the Argonaute 2 (AGO2) system, inhibiting the growth and metastasis of tumor cells to diminish disease progression." (PMID 35382893, 2022). "Lack of the m6A reader YTHDF2 can disrupt the anti-tumour and anti-viral activities of NK cells." (PMID 35572541, 2022). "The study revealed that YTHDF2 inhibits HCC progression through m6A modification by decreasing the stability of interleukin 11 (IL11) and serpin family E member 2 (SERPINE2) mRNA, which are involved in tumor angiogenesis and inflammation activation respectively." (PMID 32733807, 2020). "Finally, we found that YTHDF2 was highly expressed in GBM cells, depletion of YTHDF2 was significantly inhibited the cell proliferation and migration of GBM cells, the IHC assay also demonstrated that YTHDF2 was up-regulation in LGG and correlated with tumor grade." (PMID 35661004, 2022). "Fifth, our study only confirmed the relationship between YTHDF1, YTHDF2, CD4, CD8, and FOXP3, however did not reveal which pathway YTHDF1, YTHDF2 affects on the tumor immune profile." (PMID 36479088, 2022). "Differential expression analysis indicated that the protein expression levels of KIAA1429, RBM15, HNRNPC, HNRNPA2B1, YTHDF1, YTHDF2, and YTHDC1 were higher in tumor samples than in non-tumor samples." (PMID 32582536, 2020). "YTHDF2 expression was significantly higher in LIHC tissues than that in non-tumor tissues (P < 0.05) or paired non-tumor tissues (P < 0.05)." (PMID 33344502, 2020). "In the absence of YTHDF2, NG2+ pericytes were significantly reduced, whereas CD31+ endothelial cells largely accumulated and formed microvessels in tumor regions, defining a fundamental role for YTHDF2 in vascular normalization." (PMID 31735169, 2019). "Besides, quantitative real‐time PCR (qRT‐PCR) (for cohort 1), western blotting (for cohort 1) and immunohistochemistry (IHC) analyses (for cohort 2) in paired tumor and adjacent nontumorous tissues (ANT) confirmed the expression pattern of YTHDF2 in HCC." (PMID 38247171, 2024). "By comparing the expression of m6A related gene in the tumor group and the normal group (METTL14, YTHDF2 and YTHDF3 could not be excluded with statistical significance), mutation rates of m6A gene were all greater than 0, which could not be excluded." (PMID 37194014, 2023).
tumor (continued). "The role of the YTHDF2 gene in HNSCC has not been explored so far, whereas YTHDC2 was found to be a tumor suppressor with low expression in HNSCC samples, while its upregulation was associated with longer-term survival and the recurrence-free survival of HNSCC patients." (PMID 34207099, 2021). "In addition, YTHDF2 promotes translation but not clearance of 6-phosphogluconate dehydrogenase (6PGD) mRNA in an m6A-dependent manner by interacting with eIF3a/b, which enhances the pentose phosphate pathway (PPP) flux for tumor growth." (PMID 36999016, 2023).